KLB (klotho beta)
Diseases named in the same sentence as KLB in open-access papers (continued):
Sharing a sentence is not in itself a finding about the gene and the disease.
Anosmia (2 papers, 2017 to 2020). An inability to perceive odors. "Pathogenic variants in FGFR1 and KLB have individually been described in the setting of Kallman syndrome, a disorder characterized by hypogonadotropic hypogonadism and loss of smell (anosmia)." (PMID 33210059, 2020). "As anosmia has been associated with pathogenic variants in FGFR1 and KLB, the subjects underwent smell identification testing." (PMID 33210059, 2020). "Additionally, there has been one case of Kallman syndrome in which the affected patient carried both a missense variant in FGFR1 (R78C) and a single amino acid deletion in KLB (F777delF)." (PMID 33210059, 2020).
atherosclerosis (2 papers, 2022 to 2025). A disease characterized by the build-up of fatty material and calcium deposition in the arterial wall resulting in partial or complete occlusion of the arterial lumen. "However, high levels of TNFα and IL-1β in patients with atherosclerosis have been shown to decrease the expression of KLB." (PMID 36006939, 2022). "For example, by binding to its receptors, β-klotho (KLB) and FGF receptor 1 (FGFR1), FGF21 down-regulates hepatic sterol regulatory element binding protein-2 to inhibit cholesterol biosynthesis and induce adiponectin to inhibit atherosclerosis." (PMID 40765997, 2025).
bladder cancer (2 papers, 2018 to 2019). "We attempted to show the association between KLb and FGF/FGFR signaling in a previous study; however, human bladder cancer samples were not stained with anti-FGF and anti-FGFR antibodies." (PMID 29731962, 2018).
Coronary Artery Disease (2 papers, 2019 to 2020). "KLB polymorphism is also reportedly related to coronary artery disease and alcohol consumption." (PMID 31548436, 2019).
glioma (2 papers, 2019 to 2021). A benign or malignant brain and spinal cord tumor that arises from glial cells (astrocytes, oligodendrocytes, ependymal cells). "Even though the expression of KLB was significantly downregulated in glioma compared to levels in normal brain tissue (p < 0.05), it was still not a differentially expressed, as the |log2FC| value was <1." (PMID 31681612, 2019).
lung adenocarcinoma (2 papers, 2016 to 2019). A carcinoma that arises from the lung and is characterized by the presence of malignant glandular epithelial cells. "To explore the relationship between KLB expression levels and NSCLC progression, we examined the KLB expression in 20 lung squamous cell cancer (LSQ) samples and 30 lung adenocarcinoma (LADC) samples along with matched non-tumor control samples." (PMID 31695781, 2019).
pancreatic cancer (2 papers, 2018 to 2023). "Another study using expression data from the GEO database also suggested that KLB upregulation is associated with improved survival in pancreatic cancer patients." (PMID 37958253, 2023). "Next, the association between FGF19, FGF21, FGFR1, FGFR4, and KLB overexpression and the overall survival of pancreatic cancer patients was evaluated." (PMID 30593273, 2018).
squamous cell carcinoma (2 papers, 2022 to 2024). A carcinoma arising from squamous epithelial cells.
thyroid cancer (2 papers, 2019 to 2022). "Interestingly, a recent study focused on the role of FGF19/FGFR4/KLB signaling pathway in the development of thyroid cancers with upregulation of serum levels of KLB, FGF19, and FGFR4 in patients with thyroid cancer, compared to healthy controls." (PMID 31408968, 2019). "We examined expression levels of FGF21, FGFRs, and KLB in human thyroid tissue and the FGF21–FGFR signaling axis in thyroid cancer cells treated with recombinant FGF21 (rFGF21)." (PMID 31408968, 2019). "To determine the effect of FGF21 on tumor aggressiveness in thyroid cancer, we evaluated the expression levels of FGFRs, such as FGFRs and KLB, and phospho-FGFR in normal thyroids and thyroid cancer cell lines." (PMID 31408968, 2019).
type 2 diabetes (2 papers, 2023). "Through the development of FGF19- and FGF21 mimetics, KLB has emerged as a promising drug target for treating various metabolic diseases, such as type 2 diabetes (T2D), non-alcoholic fatty liver disease (NAFLD), and cardiovascular disease." (PMID 37260446, 2023).
alcoholic liver diseases (1 paper, 2025). A disorder caused by damage to the liver parenchyma due to alcohol consumption. "Previous studies have found that FGF21 and KLB play an important role in the treatment of alcoholic liver disease." (PMID 40786112, 2025).
diabetic kidney disease (1 paper, 2025). Progressive kidney disorder caused by vascular damage to the glomerular capillaries, in patients with diabetes mellitus. "The upregulation of KLB further modulates the lipid metabolism, iron metabolism, and lipid peroxidation, resulting in the inhibition of ferroptosis, and the attenuation of renal inflammation and fibrosis to relieve the diabetic kidney disease (DKD)." (PMID 39630101, 2025).
esophageal cancer (1 paper, 2024). A primary or metastatic malignant neoplasm involving the esophagus. "Although the impact of ADH1B on esophageal cancer risk is well documented, this is the first identification of the genetic contribution of the other four (GCKR, KLB, ALDH1A1, and ALDH2) to esophageal cancer risk." (PMID 38277453, 2024).
hepatoblastoma (1 paper, 2025). Hepatoblastoma (HB) is a malignant hepatic tumor and is the most common pediatric liver cancer. "These cholangiocyte-like cells are surrounded by embryonal hepatoblastoma cells, characterized by intermediate levels of WNT/b-catenin signaling, a high proliferation index (Ki67), and high expression of KLB, a hepatocyte transmembrane protein that plays a crucial role as a co-receptor for FGF19." (PMID 40684183, 2025).
hyperthyroidism (1 paper, 2023). Overactivity of the thyroid gland resulting in overproduction of thyroid hormone and increased metabolic rate. "The significant downregulation of KLB gene in TAO orbital adipose tissue will reduce the FGF21-induced fat catabolism, which may be one of the reasons for increased orbital adipose tissue in patients with hyperthyroidism." (PMID 37900130, 2023).
liver diseases (1 paper, 2025). "However, the tissue expression profile of KLB and its regulation in liver disease remain poorly characterized." (PMID 40937171, 2025). "Our data suggest that KLB could also play a role in other liver diseases where inflammation plays a role, such as viral hepatitis." (PMID 40937171, 2025).
small cell lung carcinoma (1 paper, 2019). Small cell lung cancer (SCLC) is a highly aggressive malignant neoplasm, accounting for 10-15% of lung cancer cases, characterized byrapid growth, and early metastasis. "Furthermore, MYC, as a driver of susceptibility to Aurora kinase inhibition in small cell lung cancer cells and tumors 45, was enriched in KLB down genes." (PMID 31695781, 2019).
vitiligo (1 paper, 2025). Generalized well circumscribed patches of leukoderma that are generally distributed over symmetric body locations and is due to autoimmune destruction of melanocytes. "The authors concluded that KLB and EIF3C are key genes in OS regulation of AA and vitiligo and that KLB and EIF3C participate in disease progression by regulating T cells and neutrophils." (PMID 40943550, 2025).
tumor (18 papers, 2012 to 2026). "Taken together, these findings have shown that a KLB-deficiency renders a tumor-promoting phenotype in NSCLC cells." (PMID 31695781, 2019). "We further performed IHC staining for Ki-67 and KLB of both the tumor and the lung tissues, and found a remarkable loss of proliferation in tumors of the KLB-OE groups." (PMID 31695781, 2019). "In discovery cohort 1, FGFR1 and Klotho beta (KLB) overexpression was associated with low tumor stage (P < 0.05), low tumor grade (P < 0.05), and better overall survival." (PMID 30593273, 2018). "According to Fisher’s exact test results, overexpression of FGFR4 (P < 0.001) and KLB (P = 0.005) were significantly associated with a low tumor grade." (PMID 30593273, 2018). "Together, these results underline a potent anti-tumor effect of KLB inhibition in HCC." (PMID 22439738, 2012). "The experiments showed that the KLB knockout had a stronger inhibitory effect on cell growth and tumor growth than the FGFR4 knockout." (PMID 41328353, 2026). "For instance, in the 21 sections that stained KLB as extremely positive, 20 (20/30) were from the non-tumor tissue group and only 1 (1/30) was from LADC tissue group." (PMID 31695781, 2019). "More specifically, 60% (12/20) of all the non-tumor samples were found to express high levels of KLB, whereas KLB was barely detectable in 30% (6/20) of all the LSQ tissues." (PMID 31695781, 2019). "In summary, exogenous βKlotho showed the similar tumor-suppressive effect to endogenous overexpression of KLB." (PMID 31695781, 2019). "Our results suggested that the KLa expression level decreased along with increase of tumor grade, contrary the KLb and KLγ expression levels increased along with increase of tumor grade." (PMID 29731962, 2018). "Taken together, our findings suggest that increased KLB expression is a frequent event in normal-to-tumor transition in hepatocytes." (PMID 22439738, 2012). "Quantitative real-time PCR analysis identified frequent elevation of KLB gene expression in HCC tumors relative to matched non-tumor tissue, with a more than two-fold increase correlating with development of multiple tumors in patients." (PMID 22439738, 2012). "The effects of FGF21 in our study may have been induced by the upregulation of FGFR signaling, which suggests that FGF21 may induce growth-stimulating effects in tumor cells in a manner dependent on the expression of FGFRs and KLB." (PMID 31408968, 2019). "Similar to LSQ samples, LADC showed lower levels of KLB vs. non-tumor tissues." (PMID 31695781, 2019). "Hence, KLB appears to play either tumor-promoting or tumor-suppressive roles depending on the cancer types, yet there is no report regarding KLB's function in NSCLC." (PMID 31695781, 2019). "The mechanism of this tumor suppressive effect of KLB in NSCLC seems to be complicated." (PMID 31695781, 2019). "Expectedly, overall tumors exhibited decreased KLB staining compared to non-tumor samples." (PMID 31695781, 2019). "We showed for the first time that KLB was frequently downregulated in LSQ and LADC compared with adjacent non-tumor tissues and revealed an association between βKlotho serum levels and tumor metastasis." (PMID 31695781, 2019). "Overexpression of KLB significantly increased the anti-tumor effects of Doxorubicin and Cisplatin." (PMID 31695781, 2019). "Taken together, these observations demonstrated that KLB could suppress tumor growth in vivo." (PMID 31695781, 2019). "Together with our previous study of UCB, KLa, KLb, and KLγ may be correlated with tumor growth." (PMID 29731962, 2018). "We hypothesized that KLb plays a role as a tumor promoter, together with FGF21 or FGF19." (PMID 29731962, 2018). "Knocking out the KLB gene using CRISPR-Cas9 technology can significantly inhibit the growth and tumor formation of HCC cells, as well as reduce the incidence of lymph node metastasis in a mouse model." (PMID 41328353, 2026).
tumor (continued). "Ninety-six percent of 53 IHC FGF19-positive tumours were assessed for FGFR4 and KLB mRNA expression." (PMID 40205008, 2025). "Consistently, decreased KLB levels were detected in LADC tissues compared with the paired neighboring noncancerous tissues, and representative staining of 3 pairs of tumor/non-tumor tissues was shown." (PMID 31695781, 2019). "The in vitro data prompted us to investigate the role of KLB in NSCLC in vivo, Using a subcutaneous model, a marked reduction in tumor growth was observed in mice receiving KLB-OE lentivirus compared with those receiving the control lentivirus." (PMID 31695781, 2019). "In contrast, FGFR1, the partner of KLB activated by FGF21, is widely expressed in adipocytes, normal luminal epithelium and tumor cells (orange staining)." (PMID 24279986, 2013). "Upregulated KLB expression (> 2-fold) in tumor tissue was observed in 25% of HCC samples and paired t-test analysis indicates an overall statistically significant increase in KLB expression in HCC tumors (Wilcoxon matched pairs test, P < 0.01)." (PMID 22439738, 2012). "In this study, we observed frequent elevation of KLB expression in HCC tumors relative to paired normal liver tissues and noted that KLB up-regulation correlated with multiple tumor formation." (PMID 22439738, 2012). "In this study, we examined the expression levels of KLB in tumor vs. non-tumor tissues of NSCLC, explored its clinical relevance as a diagnostic/prognostic biomarker, and tested its antitumor effect both in vitro and in vivo." (PMID 31695781, 2019). "As shown in our study, as long as KLB was overexpressed, tumor inhibition was observed regardless of the level of FGF19 in the cancer cells." (PMID 31695781, 2019). "Our previous report suggests that KLb acts as a tumor promoter in human UCB and that KLa does not have a significant role as a tumor suppressor or promoter in human UCB." (PMID 29731962, 2018). "We identified that KLB is downregulated in NSCLC and KLB might be a negative tumor marker in NSCLC." (PMID 31695781, 2019).
cancer (15 papers, 2012 to 2025). A tumor composed of atypical neoplastic, often pleomorphic cells that invade other tissues. "An alternative hypothesis is through a joint risk locus in KLB that independently drives alcohol consumption and cancer risk." (PMID 31998841, 2020). "Down-regulation of KLB has been reported across several cancers." (PMID 31998841, 2020). "We also found KLB copy number reduction and downregulation of expression by N stage in Oncomine database, and upregulation of KLB could inhibit the metastasis of cancer cells in vivo." (PMID 31695781, 2019). "Alpha-Klotho (KLα) and beta-Klotho (KLβ) have recently been reported to correlate with cancer prognosis in some malignancies and we previously reported the association between KLα, KLβ, and urothelial carcinoma of the bladder (UCB), indicating that KLβ acts as a tumor promoter." (PMID 29731962, 2018). "On the other hand, the role of KLb in cancer prognosis is still controversial." (PMID 29731962, 2018). "In contrast, elevated expression of KLB and FGFR4 was reported in HCC, suggesting dual functions of KLB in cancer development and progression." (PMID 32154250, 2020). "KLb affects FGF4 signaling pathway, phosphorylation of ERK1/2 and FRS2, resulting in enhancement of cell proliferation or inhibition of cancer cell apoptosis." (PMID 29731962, 2018). "In addition, abnormal expression of ABI family, member 3 binding protein (ABI3BP); klotho beta (KLB); long non-coding RNA metastasis-associated lung adenocarcinoma transcript 1 (MALAT1); and particular microRNAs, including miR-1206 and miR-612, has been observed in cancer cells." (PMID 26039424, 2015). "Using qRT-PCR, we studied KLB mRNA levels in 56 human HCC tumors and their adjacent paired normal liver tissues to identify expression level changes that accompany cancer progression." (PMID 22439738, 2012). "All of FGF19, FGFR4, and KLB expression levels are greater in cancer tissues than in normal tissues next to malignancy." (PMID 36532586, 2022). "Furthermore, KLB down genes were identified, which involved those in cell cycle, DNA replication and packaging, cell division, WNT signaling and other cancer-related pathways such as MYC, VEGF-A and MTOR." (PMID 31695781, 2019). "βKlotho (KLB), however, plays a more complex role in cancers based on current literacy." (PMID 31695781, 2019). "Since KLB overexpression induced cell apoptosis, we hypothesized that KLB could enhance the sensitivity of NSCLC cells to anti-cancer drugs." (PMID 31695781, 2019).
metabolic disease (4 papers, 2021 to 2025). A congenital disorder (due to inherited enzyme abnormality) or acquired (due to failure of a metabolically important organ) disorder resulting from an abnormal metabolic process. "To further confirm the role of liver FGF21 signaling in the improvement of metabolic disorders induced by a KD, we generated liver KLB knockdown mice using AAV injection." (PMID 38609395, 2024). "The recognition of KLB as an exciting drug target for a variety of common metabolic diseases encouraged many pharmaceutical companies to develop a multitude of FGF19 and FGF21 analogs." (PMID 37260446, 2023). "Meanwhile, pharmaceutical companies have designed and tested a multitude of FGF19- and FGF21-mimetics, recognizing KLB as a promising drug target for treating various metabolic diseases in humans." (PMID 37260446, 2023). "Thus, to provide a comprehensive evaluation of the basis of FGF21 abnormalities in metabolic disease, we analyzed the association between rs838133 and the expression of molecular actors of FGF21 responsiveness (FGFRs and KLB) in liver and adipose tissue." (PMID 34141520, 2021). "Beyond regulating metabolic disorders in T2D, FGF21 may also directly act on the heart to ameliorate DCM, as FGFR1 and KLB—the receptor and co-receptor mediating the biological functions of FGF21—are expressed in cardiac tissue)." (PMID 40724827, 2025).
cardiovascular disease (2 papers, 2023 to 2024). "The interest in developing FGF21-mimetics has also led to the recognition of KLB as a promising drug target for treating metabolic and cardiovascular diseases." (PMID 39511582, 2024).
inflammation (1 paper, 2019). Aberrant reaction of the microcirculation characterized by movement of fluid and leukocytes from the blood into extravascular tissues. "Notably, the association with ALT levels in NAFLD subjects is obviously stronger than in all subjects, which verifies the association between KLB variants and the degree of liver inflammation in the NAFLD population." (PMID 31548436, 2019).
KLB also shares sentences with these, for which no sentence is quoted: dyslipidemia (4 papers); colon tumor (3); Hyperglycemia (3); non-small cell lung carcinoma (3); alcohol use disorder (2); breast carcinoma (2); breast tumor (2); cardiac hypertrophy (2); hypogonadotropic hypogonadism (2); sarcopenia (2); adenocarcinoma (1); bacterial infections (1); brain ischemia (1); calcification (1); central obesity (1); chronic kidney disease (1); cocaine dependence (1); cognitive decline (1); cognitive deficit (1); colon cancer (1); colorectal cancer (1); congenital hypogonadotropic hypogonadism (1); craniosynostosis (1); Crohn disease (1); depression (1); developmental delay (1); diabetic cardiomyopathy (1); Diarrhea (1); endometrial adenocarcinoma (1); endometrial carcinoma (1).
A further 26 diseases each share a sentence with KLB in 1 paper.